RBM4 (RNA binding motif protein 4)
Diseases named in the same sentence as RBM4 in open-access papers (continued):
Sharing a sentence is not in itself a finding about the gene and the disease.
esophageal squamous cell carcinoma (2 papers, 2023 to 2025). Esophageal squamous cell carcinoma (ESCC) is a type of esophageal carcinoma (EC) that can affect any part of the esophagus, but is usually located in the upper or middle third. "Here we reported that RBM4 adversely impacted cellular senescence to favor glutamine-dependent survival of esophageal squamous cell carcinoma (ESCC) cells by dictating the activity of LKB1, a critical governor of cancer metabolism." (PMID 37080995, 2023). "For example, RNA binding motif protein 4 (RBM4) competitively binds Liver kinase B1 (LKB1) and induces its ubiquitination and degradation in the nucleus to evade senescence and sustain cell growth of esophageal squamous cell carcinoma." (PMID 41345704, 2025).
gastric tumor (2 papers, 2020 to 2021). "However, the relative RBM4 mRNA and the protein expression level was remarkably downregulated in the gastric tumor group, compared with the normal group." (PMID 34195294, 2021).
glioma (2 papers, 2022 to 2025). A benign or malignant brain and spinal cord tumor that arises from glial cells (astrocytes, oligodendrocytes, ependymal cells). "We also discovered that the SFs NOVA1, HNRNPC, HNRNPLL, and RBM4 are independent risk factors that affect the prognosis and immune cell infiltration of patients with glioma." (PMID 35832652, 2022). "We demonstrated that NOVA1, HNRNPC, HNRNPLL, and RBM4 were independent prognostic factors for glioma, and their expression was verified by western blotting analysis." (PMID 35832652, 2022). "Our study found that genes involved in AS events affected glioma survival including NOVA1, HNRNPC, HNRNPLL, RBM4." (PMID 35832652, 2022).
hepatocellular carcinoma (2 papers, 2021 to 2023). A malignant tumor that arises from hepatocytes. "Reduced levels of RBM4, as seen in fasted Lpin1–/– liver, are associated with poor prognosis in hepatocellular carcinoma following hepatectomy." (PMID 34494556, 2021).
Anxiety (1 paper, 2023). Intense feelings of nervousness, tension, or panic often arise in response to interpersonal stresses. "Therefore, Rbm4 knockout likely reduced anxiety-like behaviors." (PMID 37670183, 2023).
chronic gastritis (1 paper, 2016). Inflammation of the stomach that is chronic in nature. "High RBM4 protein expression was recorded in 58.6%, 56.0%, 54.2%, 51.9% and 63.1% of the stomach benign tissues in chronic gastritis, intestinal metaplasia, low-grade intraepithelial neoplasia, high-grade intraepithelial neoplasia and adjacent noncancerous tissues, respectively." (PMID 27324405, 2016).
Down syndrome (1 paper, 2016). "Interestingly, RBM4 is significantly decreased in the fetal brain in Down syndrome." (PMID 26848775, 2016).
esophageal cancer (1 paper, 2021). A primary or metastatic malignant neoplasm involving the esophagus. "Knockout of the RBM4 gene resulted in specific down-regulation of TPM1 variants V2 and V7, which might inhibit migration and filamentous group formation in esophageal cancer cells." (PMID 34804951, 2021).
fibrosarcoma (1 paper, 2007). A malignant mesenchymal fibroblastic neoplasm affecting the soft tissue and bone. "Golub-score analysis identified a relatively poor discriminatory signal of 200 genes for the fibrosarcomas, which regardless of high FDR contained several of the upregulated genes previously associated with fibrosarcoma, e.g. BMI1, H1F0, LEF1, RBM4, ITM2A, IGFBP2 and PTGS2." (PMID 17359542, 2007).
heart failure (1 paper, 2024). Inability of the heart to pump blood at an adequate rate to meet tissue metabolic requirements. "Furthermore, the 3-fold upregulation of the RNA binding motif protein 4B (RBM4) examplifies the significant genomic responses with its reactivation in heart failure driving the transcriptome into a fetal state." (PMID 39285385, 2024).
Impaired glucose tolerance (1 paper, 2013). An abnormal resistance to glucose, i.e., a reduction in the ability to maintain glucose levels in the blood stream within normal limits following oral or intravenous administration of glucose. "RBM4 null mice display low insulin levels, smaller pancreatic islets, and impaired glucose tolerance suggesting that RBM4 is involved in the regulation of insulin expression." (PMID 24051403, 2013).
kidney clear cell carcinoma (1 paper, 2025). "Firstly, we analyzed the data of kidney clear cell carcinoma (KIRC) in TCGA using bioinformatics and found that RBM4 is almost positively correlated with the gene level of autophagy pathway." (PMID 40373256, 2025).
lymph node metastasis (1 paper, 2016). "We found that reduced RBM4 protein expression was associated with lymph node metastasis, TNM stage and distant metastasis." (PMID 27324405, 2016). "Reduced RBM4 expression was significantly associated with poor differentiation (P < 0.001), lymph node metastasis (P = 0.026), distant metastasis (P = 0.036) and advanced TNM stage (P = 0.014)." (PMID 27324405, 2016). "There was a significant association between reduced RBM4 protein expression and differentiation (P < 0.001), lymph node metastasis (P = 0.026), TNM state (P = 0.014) and distant metastasis (P = 0.036)." (PMID 27324405, 2016).
Obesity (1 paper, 2023). Accumulation of substantial excess body fat. "Other genes related to obesity and/or adipogenesis were identified by our HiChIP analysis as regulators of ABD vs. GF gene transcription, such as METTL15 and RBM4." (PMID 38203607, 2023).
oesophageal cancer (1 paper, 2022). "TPM1-AS is located at the nucleus and interacts with the splicing factor RBM4 in human oesophageal cancer cells." (PMID 34750493, 2022).
prostate carcinoma (1 paper, 2015). A carcinoma that arises from epithelial cells of the prostate gland. "RBM4 was demonstrated as a tumor suppressor in various malignancies, including breast, lung, ovarian, liver, and prostate cancer." (PMID 26506517, 2015). "Overexpressing RBM4 antagonized the effect of oncogenic factors, including PTB and SRSF1 proteins in breast, lung, and prostate cancer cells." (PMID 26506517, 2015).
cancer (30 papers, 2015 to 2025). A tumor composed of atypical neoplastic, often pleomorphic cells that invade other tissues. "Modulation of RBM4 expression changed mRNA splicing patterns, with overexpression in cancer cells causing exon skipping at splice sites near RBM4 binding motifs and inhibition of tumor progression." (PMID 34065983, 2021). "We detected insertion at the intronic region of RBM4 (chr11), known to be associated with cancer and ncRNA SMG1P5 (chr16), downstream of TINAGL1 (chr1) and LOC339807 (chr2) and at an intergenic region that is 30Kb upstream of ZNF846 and 11Kb downstream of FBXL12 in chromosome 19." (PMID 28410234, 2017). "Mechanistically, our data, for the first time, showed that depletion of RBM4 played critical roles in elevating the level of SERPINE1 to promote cancer cell senescence, thereby inhibiting cancer progression." (PMID 36639375, 2023). "Taken together, depletion of RBM4-induced senescence and tumor suppression is a common role of RBM4 in distinct cancer cells." (PMID 36639375, 2023). "Collectively, these data provide a novel mechanism of RBM4, which can affect cancer progression through post-transcriptional regulation." (PMID 36639375, 2023). "Overall, our study revealed a novel mechanism of RBM4 in the regulation of tumorigenesis through controlling senescence, providing a new avenue for targeting RBM4 in cancer therapy." (PMID 36639375, 2023). "Altogether, our findings suggest that RBM4 ablation plays a critical role in inducing senescence and suppressing tumor growth both in cultured cancer cells and in a tumor xenograft models." (PMID 36639375, 2023). "Our previous study have reported that RBM4 suppresses tumorigenesis through modulating the alternative splicing of cancer-related genes." (PMID 36639375, 2023). "To further assess the role of RBM4 ablation in senescence regulation and cancer suppression in vivo, we subcutaneously inoculated H1299 cells with doxycycline-inducible depletion of RBM4, into the flanks of nude mice." (PMID 36639375, 2023). "Meanwhile, we performed KEGG analysis and found that interactions induced by depletion of RBM4 were focused on viral carcinogenesis, proteoglycans in cancer, transcriptional dysregulation in cancer, ECM-receptor interaction." (PMID 36639375, 2023). "In conclusion, we revealed that RBM4 controlled cellular senescence to regulate cancer progression via miR1244/SERPINE1 axis." (PMID 36639375, 2023). "RBM4 was generally considered as a potential tumor suppressor to inhibit cancer progression through regulating alternative splicing of cancer-related genes." (PMID 36639375, 2023). "Altogether, our study revealed a novel mechanism of RBM4 in the regulation of cancer progression through controlling senescence, providing a new avenue for targeting RBM4 in cancer therapeutics." (PMID 36639375, 2023). "RBM4 demonstrated the ability to inhibit proliferation and migration in various cancer cell lines and effectively hindered cancer progression in tumor xenograft models." (PMID 37875914, 2023). "The splicing factor RNA-binding motif 4 (RBM4) suppresses the proliferation and migration of various cancer cells by specifically controlling cancer-related splicing." (PMID 35867400, 2022). "RBM4 inhibited cell proliferation as well as migration in a variety of cancers through the specific control of cancer-related splicing." (PMID 34195294, 2021). "Reduced expression of the paralog RBM4 was also found in NSCLC, as well as in other cancer types, and shown associated with a poor prognosis." (PMID 34065983, 2021). "Recently, RBM4 has been reported as a novel tumor suppressor by controlling cancer-related splicing." (PMID 29361709, 2018).
cancer (continued). "Specifically, RBM4 induces cancer cell apoptosis by modulating BCLx splicing and shifting preference for the anti-apoptotic BCLxL to the pro-apoptotic BCLxS isoform." (PMID 29361709, 2018). "More recently, RBM4, an RNA-binding factor involved in AS, was also shown to control cancer-related splicing events, thereby affecting various cellular processes such as proliferation, apoptosis, and migration." (PMID 28493890, 2017). "RBM4 protein expression is only in 34.5% of poorly-differentiated cancers, while we found it in 54.5% of moderately-differentiated and 67.6% of well-differentiated cancers." (PMID 27324405, 2016). "In particular, TEAD4-S is controlled by RBM4, a master regulator of many cancer-related splicing events." (PMID 27291620, 2016). "Recently, RBM4, an RNA-binding factor involved in multiple aspects of cellular processes such as AS, was also demonstrated to control cancer-related splicing events affecting cellular processes such as apoptosis, proliferation, and migration." (PMID 27598998, 2016). "Such inhibition was comparable to that of RBM4 in both anchorage-dependent and -independent cell growth in two distinct cancer cell lines." (PMID 27291620, 2016). "Overexpressing RBM4 repressed the progression of various cancer cell lines, and our results showed that RBM4-modulated splicing cascade constituted a molecular mechanism regarding this phenomenon." (PMID 26506517, 2015). "Consistently, several splicing factors were found to be mutated or significantly changed in expression between cancers and normal tissue, including SRSF1, QK1, RBM4, RBM5/6/10, and hnRNP A2." (PMID 25749525, 2015). "It was recently reported that RBM4 regulates the alternative splicing of numerous cancer-related genes." (PMID 26565589, 2015). "RBM4 is a splicing inhibitor that acts as a tumor suppressor by regulating cancer-related splicing." (PMID 41451538, 2025). "Finally, to prove that the increased cancer cell death upon knockdown of circGRAMD4, RBM4 and NBR1 is mediated by increased MHC-I expression on cancer cells, cell surface MHC-I was depleted by knocking down B2M, a critical component of the MHC-I complex." (PMID 40373256, 2025). "Importantly, in all cancer cells examined, depletion of RBM4 induced senescence as judged by increased SA-β-gal activity." (PMID 36639375, 2023). "Our results demonstrated that depletion of RBM4 promoted multiple cancer cell senescence, as judged by increased SA-β-gal activity, resulting in cell cycle arrest, inhibition of cell proliferation, and alterations at protein levels of senescence related markers." (PMID 36639375, 2023). "Depletion of RBM4 induces P27-dependent cancer cell senescence and inhibits ESCC progression, which could be reversed by glutamic acid." (PMID 37080995, 2023). "RBM4 ablation induced senescence and inhibited cancer cell progression both in vitro and in vivo." (PMID 36639375, 2023). "Additionally, the xenograft tumors with inducible-depletion of RBM4 demonstrated a much slower growth rate than controls, indicating that depleted RBM4 significantly suppresses cancer progression in vivo." (PMID 36639375, 2023). "Meanwhile, RBM4 ablation inhibited cancer cell progression both in vitro and in vivo." (PMID 36639375, 2023). "We have previously shown that RBM4 might function as a potential tumor suppressor to inhibit cancer progression." (PMID 36639375, 2023). "Similarly, knockdown of RBM4 inhibited cancer cell growth and proliferation in all tested cancer cells." (PMID 36639375, 2023). "The transcription factor ATF4 drives the expression of ULBP1 gene in cancer cells, while the RNA binding protein RBM4 supports the expression of ULBP1 by inhibiting a new alternative splicing subtype of ULBP1 mRNA, and explains its mechanism of activating the body’s immune system." (PMID 35211154, 2022).
cancer (continued). "Importantly, YTHDC1-directed RBM4 splicing is governed by AURKA accumulated in the nucleus of cancer cells, therefore targeting AURKA with its nuclear translocation inhibitors effectively suppresses the oncogenic switch of RBM4 and tumor progression." (PMID 35361747, 2022). "RBM4 is a splicing inhibitor that functions as a tumor suppressor through controlling cancer-related splicing, however, whether RBM4 itself is regulated by alternative splicing remains unknown." (PMID 35361747, 2022). "Similarly, RBM4 was reported to inhibit tumor progression via specifically controlling splicing related to the apoptosis, proliferation, and migration of cancer cells." (PMID 30640723, 2019). "Deeper investigation of selected hits from the screen showed that the transcription factor ATF4 drives ULBP1 gene expression in cancer cell lines, while the RNA-binding protein RBM4 supports ULBP1 expression by suppressing a novel alternatively spliced isoform of ULBP1 mRNA." (PMID 26565589, 2015). "Therefore, targeting the senescence that is induced by depletion of RBM4 might also represent therapeutic potential for cancer treatment." (PMID 36639375, 2023). "We found that the elevated MHC-I levels on tumor cells surface after knocking out circGRAMD4, RBM4, and NBR1 decreased again with the knockout of B2M, and the corresponding changes in cancer cell death and CD8+ T cytokine levels also occurred." (PMID 40373256, 2025). "Mechanistically, downregulation of RBM4 post-transcriptionally activated SERPINE1 through reducing the level of miR-1244, thereby inducing the senescence of cancer cells." (PMID 36639375, 2023). "Taken together, our data suggest that depletion of RBM4 downregulates miR1244 by promoting the pri-miR1244 degradation, thus increasing the level of SERPINE1, which induces senescence and inhibits cancer cell growth." (PMID 36639375, 2023). "Other splicing regulatory factors, such as RNA-binding motif protein 4 (RBM4), whose expression is suppressed in cancer, is a tumor suppressor that dysregulates exon 4 skipping of NOVA alternative splicing regulator 1 (NOVA1) and intron 11 retention of PTB." (PMID 34330892, 2021). "A natural antisense TPM1-AS regulates the alternative splicing of TPM1 through an interaction with RBM4 and involves in TPM1-mediated filopodium formation and migration of cancer cells." (PMID 34804951, 2021). "Additionally, RBM4 can also antagonize the oncogenic SR protein SRSF1 to regulate BCLx splicing and inhibit cancer cell growth." (PMID 29361709, 2018).